PTH (parathyroid hormone)
Diseases named in the same sentence as PTH in open-access papers (continued):
Sharing a sentence is not in itself a finding about the gene and the disease.
Hypertension (continued). "The two MHD groups had a higher prevalence of hypertension, blood creatinine, BUN, PTH, blood phosphorus, FGF23, and D-serine than the control group, but also lower Hb, RBC, and ALB (all P < 0.01)." (PMID 36649363, 2023). "VDD+AmB/LE rats also presented alterations in the PTH-Klotho-FGF-23 signaling axis, urinary concentrating defect and hypertension, probably due to an inappropriate activation of the renin-angiotensin-aldosterone system." (PMID 31295336, 2019). "As expected, from earlier to more advanced stages of CKD, prevalence of hypertension, anemia and CVD progressively increased as the serum levels of PTH and phosphate." (PMID 30138402, 2018). "Sixty days after surgeries, VDD+Nx rats exhibited hypertension, a greater decline in renal function and plasma FGF-23 levels, renal hypertrophy, as well as higher plasma levels of PTH and aldosterone." (PMID 30370270, 2018). "Some other unknown elements might have an impact on the relation between Vitamin D and hypertension, especially in older age groups, as Sanijder reported in his review, which showed Vitamin D effect’s on blood pressure might be indirectly based on its role in parathyroid hormone performance." (PMID 28357170, 2017). "Previous reports about the relationship between a high parathyroid hormone (PTH) and low vitamin D levels with blood pressure in different hypertension groups are conflicting." (PMID 29176783, 2017). "With increasing quartile of FGF23 eGFR decreased, PTH increased and prevalence's of CVD and hypertension increased." (PMID 23587028, 2013). "Thus, in daily practice the association of high concentrations of PTH with high blood pressure may not necessarily have a causal relationship as PHPT and primary hypertension are frequent and may coincide in patients older than 50 years." (PMID 21423544, 2011). "Together, these observations imply that PTH might promote CSVD by disrupting endothelial homeostasis, promoting calcium–phosphate dysregulation, and aggravating hypertension." (PMID 41050279, 2025). "The results indicated that there was no statistical significance between PTH and hypertension in chemiluminescence assay and immunoradiometric assay, but statistical significance was observed in the electrochemiluminescence immunoassay." (PMID 38172768, 2024). "As a consequence, deficient levels of serum vitamin D might result in a lower plasma concentration of calcium, leading to a higher secretion of the parathyroid hormone (PTH), which has proven to be inversely correlated with hypertension." (PMID 39064792, 2024). "The prevalence of T2D and hypertension worldwide is rapidly increasing, and the role of PTH has not yet attracted public attention." (PMID 38172768, 2024). "Various interventional studies have shown a clear correlation between parathyroid hormone (PTH) and aldosterone; however, most of these studies executed interventions that treated hypertension via antihypertensive medication or conducted adrenalectomy (in patients with primary hyperaldosteronism)." (PMID 37968749, 2023). "Non-dipper patients had higher levels of phosphate, calcium-phosphate product, and PTH.Serum phosphate and PTH levels were predictors for non-dipper hypertension." (PMID 36364791, 2022). "In 187 nondiabetic essential hypertensive patients free of cardiovascular or renal complications, we measured serum 25-hydroxyvitamin D (25(OH)D) and parathyroid hormone (PTH) and performed a standard oral glucose tolerance test (OGTT)." (PMID 35057492, 2022). "Univariate analysis of other clinical markers including the hemoglobin level, anemia, PTH level, Kt/V level, presence of hypertension, and phosphorus level revealed no statistical correlation with the PSQI scores." (PMID 34136284, 2021). "It is noteworthy to mention that there were no serum PTH, vitamin K and sodium intake data, so their roles in osteoporotic patients with hypertension cannot be estimated." (PMID 34128860, 2021).
Hypertension (continued). "At the start of the prospective study, compared with HF-HD patients, LF-HD subjects were younger and had better control of hypertension, no cerebral strokes in the past, lower β2-microglobulin levels, and higher PTH concentrations." (PMID 26603871, 2016). "In vitamin D receptor knock-out mice renin expression is highly increased leading to hypertension and LV hypertrophy and in mice active vitamin D analogue treatment suppresses renin expression, independent of PTH." (PMID 24661355, 2014). "Neither hypertension nor PTH levels are currently covered by the guidelines for treatment of asymptomatic PHPT." (PMID 24026893, 2013). "We have also shown raised plasma renin activity in healthy subjects without hypertension after administration of PTH." (PMID 21403888, 2011). "In addition, patients with Primary Hyperaldosteronism displayed higher levels of PTH and lower plasma calcium in comparison to essential hypertension (a pathology where the ratio Ald/Ang II is elevated, but not as much)." (PMID 38785509, 2024). "PTH, hypertension, or DM did not significantly affect eGFR change." (PMID 32118376, 2020). "Furthermore, no epidemiological study of hypertension has examined both serum vitamin D and PTH levels together in Chinese." (PMID 22937036, 2012). "Left ventricular hypertrophy is a common finding in patients with PHPT although this finding may be related primarily to excess parathyroid hormone secretion and not to hypertension." (PMID 21423544, 2011). "However, in our study, we did not investigate the correlation of PTH with BP level and TOD in children with essential hypertension." (PMID 34999719, 2022).
parathyroid adenoma (232 papers, 2007 to 2026). "Molecular pathways of PTH signalling, mutations occurring in congenital hypoparathyroidism, parathyroid adenoma, and functional PC were extensively studied." (PMID 40762649, 2025). "The abnormal secretion of PTH is usually caused by a single parathyroid adenoma (80% of cases), but parathyroid hyperplasia and parathyroid carcinoma can also account for 15-20% and <1% of cases, respectively." (PMID 40529359, 2025). "This study highlights the diagnostic value of the PTH-WO test as a complementary tool for the preoperative localization of parathyroid adenomas, particularly in cases with inconclusive or discordant imaging findings." (PMID 41036141, 2025). "This study identified that PTH and the change in calcium had clear associations with successful parathyroid adenoma localisation, likely due to their significant correlation with adenoma size." (PMID 40979160, 2025). "Parathyroid adenoma size, serum PTH and change in calcium levels had a clear association with successful parathyroid adenoma localisation." (PMID 40979160, 2025). "Evaluation of serum calcium and parathyroid hormone levels is crucial for a suspected neck hematoma associated with parathyroid adenoma." (PMID 39210926, 2024). "The etiology of PHPT primarily involves the following causes as a source of elevated PTH: parathyroid adenoma (85-90% of cases), parathyroid hyperplasia (10‐15% of cases, sporadically or as part of genetic syndromes), and parathyroid carcinoma (less than 1%)." (PMID 39040613, 2024). "Parathyroid adenomas are benign neoplasms originating from the parathyroid glands and cause excessive parathyroid hormone production." (PMID 38024058, 2023). "Among the imaging parameters, PTH/Svol was associated with both the functional status of the parathyroid adenoma and the severity of the disease." (PMID 37892003, 2023). "Here are some ways in which a parathyroid adenoma can mimic rickets: 1) bone demineralization: excessive production of PTH by a parathyroid adenoma can cause increased bone resorption, resulting in bone demineralization." (PMID 37790151, 2023). "Further studies are needed to explore the role of vitamin D in the localization of parathyroid adenomas on the one hand, and to properly document the association between BMI and preoperative PTH concentration on the other." (PMID 36268338, 2022). "The main causes of persistent PTH elevation in transplanted patients are low vitamin D levels, hyperplasia, or adenoma of the parathyroid gland (which mainly affects kidney graft recipients) and impaired renal function." (PMID 29720961, 2018). "VD deficiency, otherwise a commonly recognized condition, is associated with larger parathyroid adenomas and higher levels of PTH before and after surgery for primary HPT." (PMID 27928436, 2016). "VD deficiency is associated with larger parathyroid adenomas and higher levels of PTH before and after surgery for primary HPT." (PMID 27928436, 2016). "The sensitivity of sestamibi scintigraphy has been associated with the size of the parathyroid adenoma, the level of serum calcium and PTH, as well as the oxyfilic content of tumour, and concomitant thyroid disease." (PMID 26542689, 2015). "In conclusion, PTH-WO is a valuable tool in enhancing the diagnostic accuracy of parathyroid adenomas; however, its reliability is influenced by various factors, including aspiration technique and the biological and morphological characteristics of the adenoma." (PMID 41036141, 2025). "PTH normalization, following surgical removal of parathyroid adenoma, reverts the bone mass loss." (PMID 32326947, 2020). "Thus, PTH hypersecretion, caused by a parathyroid adenoma, hyperplasia, or carcinoma, leads to increase of the extracellular calcium." (PMID 24685256, 2014).
parathyroid adenoma (continued). "Our results on the ontogeny of these extra-parathyroid PTH-expressing cells provides insight into understanding the etiology of some hyperparathyroid disorders caused by ectopic parathyroid glands and intrathymic parathyroid adenomas." (PMID 21203493, 2010). "Cervical ultrasound demonstrated a vascularized hypoechoic lesion posterior to the left thyroid lobe, consistent with a parathyroid adenoma, further confirmed by fine-needle aspiration with PTH washout (2075 pg./mL)." (PMID 41657575, 2026). "Case presentation: We describe a case of a female patient with confirmed PHPT and a suspected parathyroid adenoma who underwent FNAB with PTH washout measurement as part of the diagnostics." (PMID 42194540, 2026). "Normally, with the increase in the size of the parathyroid adenoma, the amount of PTH also increases, and the patient becomes symptomatic." (PMID 41473886, 2026). "Rapid intraoperative PTH (ioPTH) measurement: 37.9 pg/ml, resection was successful, and postoperative histopathology supported: parathyroid adenoma." (PMID 40161883, 2025). "PTH-WO values vary according to the ultrasonographic dimensions of parathyroid adenomas and are measured at higher levels in cystic adenomas." (PMID 41036141, 2025). "Following the removal of the prior 2 normal parathyroids there was less PTH to compete, and subsequently the parathyroid adenoma was identified." (PMID 39733582, 2025). "Parathyroid adenomas are benign tumors of the parathyroid glands, which regulate calcium levels through the secretion of parathyroid hormone (PTH)." (PMID 41196525, 2025). "11C-methionine is retained in the parathyroid adenomas due to its involvement in the synthesis of parathyroid hormone precursors." (PMID 40060374, 2025). "The findings of parathyroid adenoma, high levels of PTH, CKD on dialysis, and imaging results raised the possibility of a brown tumor of the bone." (PMID 40922257, 2025). "As in parathyroidectomized patients, eucalcemic PTH elevations have also been detected in patients with ablated parathyroid adenoma." (PMID 41509929, 2025). "Generally, females are affected between the ages of 50 and 60 due to the hypersecretion of PTH by a parathyroid adenoma." (PMID 39958142, 2025). "On the day of admission, patients with a single adenoma had a mean PTH level of 311 pg/mL (SD = 346), whereas patients with two parathyroid adenomas had a mean PTH level of 499.30 pg/mL (SD = 523) (p < 0.05)." (PMID 39941666, 2025). "The patient’s mildly elevated calcium, high PTH, and the CT finding of a lesion adjacent to the oesophagus were consistent with a parathyroid adenoma." (PMID 41556024, 2025). "The conventional value of preoperative PTH in PCs is around three to 10 times higher than the upper limit, much higher than in parathyroid adenomas." (PMID 40026929, 2025). "Previous medical history included parathyroid adenomas with a long history of increased PTH and kidney tumor." (PMID 40115416, 2025). "Surgical removal of a parathyroid adenoma led to a reduction in serum PTH and total calcium levels, along with an increase in inorganic phosphate level." (PMID 39941666, 2025). "Our study demonstrated that the ultrasonographic dimensions of parathyroid adenomas were consistent with PTH-WO levels." (PMID 41036141, 2025). "Intraoperative manipulation of parathyroid adenomas, such as through mechanical stimulation (squeezing or manual rubbing), has been shown to lead to increased PTH secretion." (PMID 39831132, 2025). "Patients with atypical parathyroid tumor had significantly higher pre-operative PTH levels, intermediate calcium levels, falling between those of parathyroid adenoma and parathyroid carcinoma patients and larger gland diameter." (PMID 41160283, 2025).
parathyroid adenoma (continued). "This case should raise awareness among physicians of the possibility of MEN1 in patients with urinary tract stones, and that timely assessment of blood calcium and PTH levels is essential, allowing early detection of parathyroid adenoma and surgical treatment." (PMID 40421248, 2025). "The presence of parathyroid adenoma with normal serum parathormone (PTH) and calcium levels is extremely rare, according to the existing literature." (PMID 40821457, 2025). "Patients who underwent removal of an atypical parathyroid adenoma were significantly less likely to achieve normalization of PTH levels on the first day after surgery than were those with typical adenomas (9.3% vs. 35.5%; p < 0.05)." (PMID 39941666, 2025). "In our study, the relationship between the ultrasonographic features of 128 parathyroid adenomas and PTH-WO levels was evaluated, and the factors affecting the diagnostic accuracy of this method were investigated." (PMID 41036141, 2025). "Subsequently, thyroid carcinoma and parathyroid adenoma were treated with cervical surgery, with careful recurrent laryngeal nerve preservation, and postoperative normalization of serum calcium and PTH levels confirmed successful parathyroid resection." (PMID 40525079, 2025). "Patients with primary parathyroid adenomas exhibited the expected biochemical hyperactivity, with significantly increased ionic calcium (mean ≈ 8.6 mg/dL) and elevated PTH (mean ≈ 105 pg/mL), confirming functional autonomy of the adenomatous glands." (PMID 41373711, 2025). "PTH collection from the internal jugular veins was positive regarding the confirmation of parathyroid adenoma laterality in 22 cases (75.86%) and failure in 7 cases (24.14%), (p-value = 0.001)." (PMID 40209343, 2025). "They found that miR-199b-5p expression levels were significantly decreased and negatively correlated with parathyroid hormone levels in sporadic parathyroid adenomas and upregulated in the inherited counterpart." (PMID 40507887, 2025). "After excluding cystic adenomas, the significant relationship between the PTH-WO value and adenoma size persisted in solid parathyroid adenomas (n = 98)." (PMID 41036141, 2025). "Early and accurate detection of ectopic parathyroid adenomas is crucial for accurate diagnosis and improved patient outcomes, as timely surgical intervention can prevent complications and normalize serum PTH and calcium levels." (PMID 40709121, 2025). "This study evaluated the relationships between PTH-WO levels and the size, location, morphological characteristics, B-mode and Doppler ultrasonographic findings, and demographic data of parathyroid adenomas in patients diagnosed with PHPT." (PMID 41036141, 2025). "This study aimed to evaluate the relationship between ultrasonographic features of parathyroid adenomas and parathyroid hormone washout (PTH-WO) values." (PMID 41036141, 2025). "The patient's calcium and PTH levels returned to normal after the parathyroid adenoma was excised, and subsequent pancreatic surgery helped to ease the patient's pancreatitis." (PMID 41001160, 2025). "Our study also highlights the relationship between larger adenomas and higher levels of PTH, supporting the principle that adenomas accompanied by higher PTH levels were more likely to be localised due to parathyroid adenoma size." (PMID 40979160, 2025). "In patients with parathyroid adenomas, dispersed cells prepared from in vitro pathological glands and normal parathyroid glands were incubated with various concentrations of Ca, and PTH secretion was evaluated." (PMID 40810066, 2025). "This study focused on the role of Epfn in the regulation of PTH transcription in vivo and in vitro, and the findings demonstrated a link between the reduced Epfn level and the overproduction of PTH in parathyroid adenomas." (PMID 40164571, 2025).